PDPN (podoplanin)
Diseases named in the same sentence as PDPN in open-access papers (continued):
Sharing a sentence is not in itself a finding about the gene and the disease.
cancer (continued). "To overcome this problem, we used single cell based live-imaging based on the Fucci (fluorescent ubiquitination-based cell cycle indicator) system to visualize the differences between PDPN+ and PDPN− cancer cells, with respect to cell cycle status, viability, and death." (PMID 28059107, 2017). "Overexpression of podoplanin results in a lower interaction of CAFs with carcinoma cells." (PMID 28416768, 2017). "Due to lack of consistent results about these biological markers in cervical lesions, we noticed the importance to evaluate the profile of VEGF and PDPN immunoexpression and show their relevance as predictor for cancer progression, which have a great potential to prevent metastasis development." (PMID 27313335, 2016). "In addition, PDPN interacts with the standard isoform of the hyaluronan receptor CD44s on the surface of carcinoma cells." (PMID 26893367, 2016). "Podoplanin is a small membrane mucin, which is involved in cell migration and cancer cell invasion." (PMID 26095281, 2015). "PDPN is therefore a notable candidate for development of cancer-targeted therapy." (PMID 26528756, 2015). "The bulk of the PDPN protein, about 150 amino acids, lies outside of the cell and could serve as an ideal target to combat cancer growth and progression." (PMID 25826087, 2015). "PDPN has emerged as a functionally relevant cancer biomarker and chemotherapeutic target." (PMID 25826087, 2015). "C6/Lung cells were used as the cancer cell model to address whether 2CP is able to inhibit PDPN-induced TCIPA." (PMID 26528756, 2015). "Taken together, these data suggest that antibodies and lectins may be utilized to combat OSCC and other cancers that express PDPN." (PMID 25826087, 2015). "The apparently contradictory PDPN activities suggest that podoplanin might function as a factor promoting or suppressing cancer metastatic potential and progression depending on the tissue- and organ-specific environment, and on the cellular context." (PMID 24797369, 2014). "In this study, we developed a cancer-specific mAb (CasMab) against human podoplanin." (PMID 25080943, 2014). "Therefore, a cancer-specific anti-podoplanin mAb is necessary for molecular targeted therapy against podoplanin-expressing cancers." (PMID 25080943, 2014). "A neutralizing monoclonal antibody (mAb; NZ-1) can block the association between podoplanin and C-type lectin-like receptor-2 (CLEC-2) and inhibit podoplanin-induced cancer metastasis, but NZ-1 reacts with podoplanin-expressing normal cells such as lymphatic endothelial cells." (PMID 25080943, 2014). "In this study, we established a cancer-specific mAb (CasMab) against human podoplanin." (PMID 25080943, 2014). "Our observation agrees with several studies which demonstrated involvement of podoplanin in cell migration and invasiveness during cancer progression, and in the promotion of epithelial-mesenchymal transition through down-regulation of epithelial genes and up-regulation of mesenychymal markers." (PMID 24797369, 2014). "Although the molecular mechanisms of PDPN expression in CAFs are not clear, and CAFs have functional heterogeneity, we found that PDPN+ CAFs play an important role in cancer cell invasion in association with the expression of CD10, MMP2, and MMP3." (PMID 24354864, 2013). "Several types of cancer may also express PDPN, such as squamous cell carcinomas, soft tissue tumors, and brain tumors." (PMID 24354864, 2013). "The differences in biological function of PDPN+ CAFs in diverse cancers might therefore be based on the characteristics of their origins." (PMID 24354864, 2013). "Some of the biological functions of PDPN in cancer cells have been partially elucidated in several studies, but the biological characteristics of PDPN-expressing stromal fibroblasts are largely unknown." (PMID 24354864, 2013). "Interestingly, in these cases, as in those from cancer studies, PDPN expression is usually correlated with inflammatory or disease settings." (PMID 22988448, 2012).
cancer (continued). "The exact molecular function of cancer cell expressed podoplanin is currently studied." (PMID 24551781, 2012). "Calretinin, CK 5/6, podoplanin, or mesothelin was often expressed in other cancers." (PMID 22768319, 2012). "Knockdown of PDPN in CAFs resulted in enhanced cancer cell migration in a transwell assay." (PMID 22988448, 2012). "The bulk of the PDPN protein, about 150 amino acids, lies outside of the cell and could serve as an ideal target to combat cancer invasion and metastasis." (PMID 22844530, 2012). "Interestingly, increasing data show that podoplanin is upregulated on the invasive front of human cancers." (PMID 21385358, 2011). "Podoplanin might therefore be an important target not only in cancer therapy but also in the treatment of RA." (PMID 21385358, 2011). "In the case of SCCs, podoplanin is mainly expressed in peripheral cancer cells in solid nests." (PMID 21034514, 2010). "All together, the findings obtained from our animal model in the present study were experimentally able to support recent clinicopathological evidence suggesting that the expression of podoplanin in cancer cells is a favorable prognostic marker of patients with lung SCC." (PMID 21034514, 2010). "Podoplanin expression is attracting interest as a marker for cancer diagnosis and prognosis." (PMID 20196862, 2010). "Moreover, well-differentiated carcinomas exhibited significantly higher levels of podoplanin, compared to moderately or poorly differentiated carcinomas (P = 0.04)." (PMID 20196862, 2010). "Podoplanin-positive carcinoma cells could be visualized inside lymph vessels (irrespective of vessel location) in 43% of the cases (44/103, LI positive)." (PMID 20698954, 2010). "Additionally, our findings suggest that PDPN could serve as a predictive biomarker for immunotherapy resistance in cancer patients." (PMID 41573582, 2025). "In addition, to better understand the role of POSTN and PDPN in cancer development, similar to our previous work and that of other authors, it was performed an analysis of the correlation of the expression of these two proteins with the expression of the Ki67 antigen." (PMID 41361308, 2025). "PDPN may contribute to metastasis and infiltration of cancer cells and be a prognostic marker." (PMID 40554484, 2025). "Interestingly, the excluded phenotype was associated with upregulation of TGFβ and high expression of markers for cancer-associated fibroblasts, such as FAP or PDPN, which could form a barrier to prevent T-cell infiltration." (PMID 39669575, 2024). "Interestingly, PDPN-positive CAFs have been shown to predict poor cancer prognosis." (PMID 39123425, 2024). "Additionally, the presence of TF and PDPN in cancer cells, as well as monocytes/macrophages, might contribute to blood clotting reactions and the clumping of platelets." (PMID 39682237, 2024). "PDPN is a cell surface mucin‐like glycoprotein that is involved in the normal development of the lungs, kidneys, and lymphatic system but is overexpressed in several tumors and may also be important in the development and progression of malignant tumors." (PMID 39487962, 2024). "Furthermore, we investigated changes in cancer-associated fibroblast (CAF) subtypes in scramble-control and gal 4–KD tumors by performing single-cell sequencing on flow cytometry–sorted podoplanin+ (PDPN+) cells." (PMID 36478037, 2023). "Therefore, treatment with a ROCK inhibitor may significantly decrease the invasion area and the number of invaded cancer cells owing to podoplanin overexpression-dependent enhancement of RhoA activity in CAFs." (PMID 36376711, 2023). "Interestingly, aberrant O-glycosylation was detected on cancer-origin PDPN." (PMID 34322381, 2021). "In addition, cancer cells could induce platelet aggregation and thrombus by directly binding via their cell surface podoplanin (PDPN) to C-type lectin receptor type 2 (CLEC-2) on the platelets." (PMID 34722319, 2021).
cancer (continued). "Other read-outs for cancer stemness associated genes such as BMI-1, Nanog, Sox2, Oct-4, SALL4, GLI-1, Ep-CAM, and Podoplanin (PDPN) are involved in regulating CSC populations, leading to enhanced proliferation, invasiveness, therapy resistance, and metastatic capacity." (PMID 32560537, 2020). "This study suggests that cancer cell adhesion to the extracellular matrix (ECM) is linked to mutations in the atypical cadherin and tumor suppressor FAT3 in a subset of patients, as well as to a mesenchymal–mesothelial phenotype involving the upregulation of calretinin and podoplanin." (PMID 32533757, 2020). "Finally, PDPN is expressed in invasive neuronal cancer stem cells." (PMID 31195298, 2019). "Thus, the use of our pull down screening system could facilitate the effective selection of potential inhibitor compounds of the podoplanin-CLEC-2 interaction for cancer therapy." (PMID 31553741, 2019). "Besides PDPN, many of these molecules, such as IFI6, IFI27, IFI44L, and BOP1, also have been reported to be associated with carcinogenesis and treatment in other types of cancers." (PMID 31321241, 2019). "Thus, PDPN expressed in stromal fibroblasts may be involved in cancer progression, leading to a poor prognosis via mechanisms of multiple growth factors derived from activated platelets." (PMID 28702871, 2018). "PDPN has been reported to be a cancer stem cell marker; therefore, immunotherapy using specific antibodies against hPDPN may eradicate cancer stem cells in cancers." (PMID 26416352, 2015). "Indeed, PDPN signaling promotes invasion and metastasis of many types of cancer cells." (PMID 25826087, 2015). "Therefore, we used a cancer-type podoplanin, which is expressed in LN229/hPDPN cells." (PMID 25080943, 2014). "Therefore, we hypothesized that the differences in the invasive potential of cancer cells were due to PDPN expression in CAFs." (PMID 24354864, 2013). "Stromal fibroblasts surrounding cancer cells may also express PDPN." (PMID 24354864, 2013). "However, in nearly every instance where PDPN is expressed, whether by FRCs or cancer cells, there will be CLEC-2+ cells in the nearby environment, including DCs or platelets." (PMID 22988448, 2012). "This study is the first to demonstrate the presence of well-developed microvilli at membranous PDPN-stained sites in EMPM of FFPE sections and establish their utility in the pathological differential diagnosis of thoracic malignant tumors." (PMID 40428290, 2025). "TGF-β was commonly expressed by multiple cell types, including cancer cells, stromal cells and BECs, and its expression was upregulated in metastatic LNs, potentially driving the expression of MGP, FN1, SOX4, PDPN, and HEY1 in LECs." (PMID 41249124, 2025). "To investigate PDPN localization, we performed immunohistochemical staining on matched NDT, NAT and primary carcinoma of a cohort of 20 CRC patients." (PMID 40842027, 2025). "We developed CasMabs against podoplanin (LpMab-2 and LpMab-23), podocalyxin (PcMab-6), and HER2 (H2Mab-250) by evaluating the reactivity against cancer and normal cells in flow cytometry." (PMID 38339219, 2024). "Similar to the cancer tissue samples, a significant weak positive correlation was also seen between MMP2 and PDPN and between THY1 and PDPN in adjacent normal tissues." (PMID 39335130, 2024). "Around the cancer nest regions, the CX3CL1 enrichment patient group exhibited an increased number of PDPN+ structures compared with CX3CL1-stable patients." (PMID 38775151, 2024). "Detection of differential markers subtyped the cells of mesenchymal origin (vimentin, desmin, cadherin-11, podoplanin, CD74, S100A4, CD44, FAP), which vary according to the functional differentiation and specialization in sites of cancer tissue." (PMID 39575252, 2024). "Podoplanin (PDPN), also known as T1α/Aggrus/gp36, is a type I transmembrane sialo-glycoprotein that plays essential roles in cancer progression and metastasis." (PMID 37894446, 2023).
cancer (continued). "Ischemia induced upregulation of PDPN expression on CD45- cells in the interstitial space, but PDPN expression was also detected in CD45+ cell infiltrates, which was described previously in models of bacterial infection and human cancer." (PMID 37691936, 2023). "By combining FISH and multiplex IHC, we stained metastatic lesions in MMTV-PyMT lungs for PTN (RNA-FISH), PyMT antigen (cancer cell marker), CD31 (endothelial marker), CD45 (pan-immune cell marker), and podoplanin (fibroblast, lymphatic maker)." (PMID 36828390, 2023). "Some cancer stem cell markers have shown a positive correlation with the degree of dysplasia, including CD44, retinal dehydrogenase 1, prominin-1, and podoplanin." (PMID 37893561, 2023). "We have developed CasMabs that target podoplanin (PDPN), which recognize the aberrant glycosylation patterns typical of cancer cells." (PMID 37886932, 2023). "Ectonucleoside triphosphate diphosphohydrolase 1 (ENTPD1) is positively correlated with LYVE1, PDPN, and VEGFC in the LECs of patients with different cancers." (PMID 36067135, 2022). "Most cancers presented PDGFRA, PDGFRB, PDPN, ACTA2, and FAP hypermethylation compared to normal samples." (PMID 36032075, 2022). "Antibodies that inhibit the interaction between PDPN and CLEC2, CAR-T cells, biologics, and synthetic compounds that target PDPN can inhibit cancer progression in preclinical models." (PMID 35565252, 2022). "Recently, it was found that there were an increased number of podoplanin‐positive lymphatic vessels and CD68‐positive histiocytes in cancer patients treated with the radiotherapy." (PMID 36267823, 2022). "To investigate the grade of cancer cells, we explored alveolar type I (AT1) and alveolar type II (AT2) cells with annotated markers, including PDPN, AGER, ABCA3, and SFTP gene families." (PMID 35874770, 2022). "Instead of the EMT process, PDPN recruits ERM proteins to modulate the actin cytoskeleton in a RhoA-dependent manner, consequently promoting cancer cell migration and invasion." (PMID 34987523, 2021). "Potential relationships with the expression of tumoral PD-L1 and cancer stem cell (CSC) markers (NANOG, SOX2, OCT4, Nestin and Podoplanin (PDPN)) are assessed." (PMID 34201050, 2021). "The interaction of podoplanin with the tetraspanin CD9 is mediated by CD9 transmembrane domains 1 and 2, and this interaction impairs cancer metastasis by inhibiting platelet aggregation." (PMID 34184727, 2021). "On the other hand, podoplanin has been proposed as a CSC marker in esophageal and cervical SCCs —although its relationship with cancer stemness is far to be clear." (PMID 33003440, 2020). "Podoplanin-CLEC-2 interaction further enhances the immunosuppressed microenvironment, facilitating spread and growth of the cancer." (PMID 32244723, 2020). "The transmembrane glycoprotein podoplanin (PDPN) is upregulated in some tumors and has gained attention as a malignant tumor biomarker." (PMID 32581653, 2020). "The interaction between PDPN and CLEC-2 not only promotes cancer cell-induced platelet aggregation but also plays an essential role in physiological processes." (PMID 31208371, 2019). "Podoplanin-positive cancer cell lines promote platelet activation and especially platelet TGF-β expression which in turn triggers EMT transition of the cancer cells." (PMID 30791448, 2019). "Our results suggest that podoplanin ligation can represent a novel approach to modulate LEC migration and tube formation in response to VEGF isoforms, key processes during cancer- and inflammation-induced lymphangiogenesis." (PMID 28727496, 2018).
cancer (continued). "Because our previously established neutralizing antibodies suppress interaction between podoplanin and CLEC-2, they are capable of inhibiting hematogenous metastasis of podoplanin-expressing cancer cells." (PMID 30279963, 2018). "As shown here, higher PDPN expression is due to hypoxia under which condition, the addition of CCL21 is required to help the CAF/cancer cell interaction." (PMID 28416768, 2017). "It has been reported that CD44, the major hyaluronan (HA) receptor and one of the cancer stem cell (CSC) markers, is a novel partner for Podoplanin." (PMID 28912668, 2017). "Human podoplanin (hPDPN), which binds to C‐type lectin‐like receptor‐2 (CLEC‐2), is involved in platelet aggregation and cancer metastasis." (PMID 28101903, 2017). "Another non-cytotoxic 5-nitrobenzoate compound, 2CP, specifically inhibited the podoplanin-CLEC-2 interaction and TCIPA resulting in anti-cancer metastatic activity in vivo in the experimental animal model." (PMID 28752248, 2017). "Podoplanin (PDPN/Aggrus/T1α/gp36/OTS-8), a type I transmembrane sialoglycoprotein, is involved in platelet aggregation, cell invasion, and cancer metastasis." (PMID 25723283, 2015). "Signaling by extracellular matrix MMPs, cell surface sialoglycoprotein podoplanin, intracellular small GTP-binding p21Rac1, and vimentin proteins are well known to regulate processes of cellular motility, migration and invasion of cancer cells." (PMID 24598827, 2014). "In addition to podoplanin, a type III intermediate filament cytoskeletal protein, vimentin, that regulates cytoskeletal interactions such as adhesion, migration and signaling, is also frequently overexpressed in invasive cancer cells and associates with metastasis and poor prognosis." (PMID 24598827, 2014). "To develop novel anti-podoplanin mAbs, we immunized mice with LN229/hPDPN cells, which possess cancer-type glycan patterns, including highly sulfated polylactosamine and aberrant sialylation." (PMID 25080943, 2014). "Previous work has reported the podoplanin and CD44 double positive cells possess cancer stem cell properties in A431 cell line." (PMID 22745808, 2012). "In particular, the interaction of PDPN cytoplasmic tail appeared to be critical in the rearrangement of the actin cytoskeleton and modulation of small Rho GTPases both involved in EMT during cancer." (PMID 40842027, 2025). "Moreover, studies across various cancers identified N-cadherin, Tenascin-C, P-cadherin, NFATc, NR2F, PDPN and LAMC2 as drivers of the p-EMT state." (PMID 40764669, 2025). "In veterinary medicine, these proteins contribute to better diagnosis and treatment of cancer in patients and may indicate potential animal models for studying relevant cancers in humans with POSTN and PDPN being among such proteins." (PMID 41361308, 2025). "Nevertheless, future investigations should include the assessment of circulating podoplanin levels and explore additional mechanisms that may affect CLEC-2 detectability and regulation in the cancer setting." (PMID 41209555, 2025). "Podoplanin (PDPN), a lymphatic vessel marker, is also a CAF marker in certain cancers." (PMID 39451200, 2024). "The A1 aptamer has the potential to be developed as a biomedical tool for the analysis of PDPN expression and as an effective pharmacological agent in the inhibition of cancer metastasis and various pathological conditions connected with the activation of CELC-2 by PDPN." (PMID 39451677, 2024). "Since kidney cells, however, potentially express PDPN, we sought to identify a cancer cell line with CA9 but not PDPN under normoxic conditions as found in peripheral blood where platelets are predominantly found." (PMID 39768175, 2024). "They validated the nonrandom expression of PDPN among GBM cells and its correlation with cell subpopulations enriched in mesenchymal differentiation signatures, cancer-related inflammation, and coagulation-associated genes." (PMID 39682237, 2024).